NCDN (neurochondrin)
Description:
Probably involved in signal transduction in the nervous system, via increasing cell surface localization of GRM5/mGluR5 and positively regulating its signaling. Required for the spatial learning process. Acts as a negative regulator of Ca(2+)- calmodulin-dependent protein kinase 2 (CaMK2) phosphorylation. May play a role in modulating melanin-concentrating hormone-mediated functions via its interaction with MCHR1 that interferes with G protein-coupled signal transduction. May be involved in bone metabolism. May also be involved in neurite outgrowth (Probable).
Synonyms: NCDN-1; NCDN-2; NEDIES
Tractability: Antibody: UniProt places it where antibodies can reach, with medium confidence. PROTAC: ubiquitination databases record sites on it; its protein half-life has been measured.
Gene: Protein-coding gene on chromosome 1 (35,557,456 to 35,567,274, forward strand). Ensembl gene ENSG00000020129.
Subcellular location: Cytoplasm, cytosol; Endosome membrane; Cell projection, dendrite; Postsynapse
Subcellular location (Human Protein Atlas): Cytosol
Gene Ontology:
Molecular function: protein binding
Biological process: neuron projection development; regulation of neuronal synaptic plasticity; regulation of postsynaptic neurotransmitter receptor internalization
Cellular component: cytosol; membrane; axon; dendrite; endosome membrane; neuronal cell body; nucleus; postsynapse; glutamatergic synapse; neuron projection; perikaryon
Genetic constraint (gnomAD): Loss-of-function variants: 9 observed, 60.23 expected, observed/expected ratio (o/e) 0.15, 90% interval 0.089 to 0.26. The upper end of that interval is the gene's LOEUF score, 0.26, which puts it in group 1 of 6, group 1 being the genes least tolerant of losing a copy. Missense variants: 578 observed, 991.53 expected, observed/expected ratio (o/e) 0.58, 90% interval 0.54 to 0.62. Synonymous variants: 409 observed, 452.23 expected, observed/expected ratio (o/e) 0.9, 90% interval 0.83 to 0.98.
Homologues: Orthologues: chimpanzee NCDN (100% identical), macaque NCDN (99% identical), rabbit NCDN (98% identical), mouse Ncdn (98% identical), rat Ncdn (98% identical), dog NCDN (98% identical), pig NCDN (97% identical), guinea pig NCDN (78% identical), tropical clawed frog ncdn (48% identical), zebrafish ncdn (33% identical), Drosophila melanogaster Neurochondrin (27% identical).
Diseases named in the same sentence as NCDN in open-access papers:
NCDN is named in the same sentence as 22 diseases in open-access papers, as found by Europe PMC text mining. Sharing a sentence is not in itself a finding about the gene and the disease. The quoted sentences say what the papers report.
Autoimmunity (3 papers, 2020 to 2024). The occurrence of an immune reaction against the organism's own cells or tissues. "So far, neurochondrin autoimmunity is reported in autoimmune encephalitis, rapidly progressive rhomboencephalitis with cerebellar ataxia and brainstem signs, cerebellar degeneration, chorea, and Alzheimer’s disease." (PMID 39376559, 2024). "Our case expands the spectrum of neurochondrin autoimmunity to disorders involving major cognitive disorder such as AD dementia." (PMID 35785337, 2022). "As neurochondrin is located intracellularly, the pathogenicity of neurochondrin antibodies is unclear and they might only be a biomarker of autoimmunity including T-cell-mediated neurotoxicity." (PMID 32824982, 2020). "Furthermore, we speculate that neurochondrin autoimmunity might have triggered an acceleration of AD symptoms as its onset was reported only after a short 6-month interval via a synergistic or negatively additive hybrid mechanism of action between neurodegeneration and autoimmunity." (PMID 35785337, 2022). "At this time, his autoimmune/paraneoplastic encephalitis, CSF (Mayo ID: ENC2), was updated to show positive anti-neurochondrin antibodies at a titer of 1:512." (PMID 39376559, 2024).
cerebellar ataxia (3 papers, 2021 to 2025). A neurological syndrome characterized by clumsy and uncoordinated movement of the limbs, trunk, and cranial muscles. "The neurochondrin-associated neurological disorder is rare and its principal clinical manifestations observed so far are cerebellar ataxia, rhombencephalitis, and hyperkinetic movements such as chorea." (PMID 39376559, 2024). "Per review of literature, only 19 cases with cerebellar ataxia and positive anti-neurochondrin antibody testing have been reported." (PMID 39376559, 2024). "Anti-neurochondrin antibodies have been described in patients with long-standing cerebellar or brainstem symptoms, while Adapter-related protein complex 3 beta-2 subunit (AP3B2) antibodies are more frequently associated with a subacute form of cerebellar ataxia." (PMID 40881707, 2025).
epilepsy (2 papers, 2021 to 2024). A brain disorder characterized by episodes of abnormally increased neuronal discharge resulting in transient episodes of sensory or motor neurological dysfunction, or psychic dysfunction. "This study contributes to the body of evidence supporting the role of neurochondrin antibody in epilepsy." (PMID 39376559, 2024). "In combination, our data provide evidence that bi-allelic and de novo variants in NCDN cause a clinically variable form of neurodevelopmental delay and epilepsy, highlighting a critical role for NCDN in human brain development." (PMID 33711248, 2021). "However, seizures were not reported, suggesting that NCDN haploinsufficiency does not necessarily cause epilepsy." (PMID 33711248, 2021).
neuroblastoma (2 papers, 2019 to 2021). Neuroblastoma (NB) is the most common solid, extracranial childhood tumor. "To clarify the pathophysiological effects of the observed NCDN variants, we then generated a neural cell model depleted of NCDN by using the human neuroblastoma line SH-SY5Y." (PMID 33711248, 2021).
schizophrenia (2 papers, 2015 to 2022). A major psychotic disorder characterized by abnormalities in the perception or expression of reality. "Neurochondrin knockout led to a behavioral phenotype associated with an animal model for schizophrenia, as indexed by alterations both in sensomotoric gating and psychotomimetic-induced locomotor activity." (PMID 28248263, 2015). "Previous studies in mice have shown that forebrain-specific knockout of NCDN causes impaired mGluR5 dependent long-term potentiation (LTP) and long-term depression (LTD), as well as schizophrenia-like phenotypic behaviors." (PMID 35151370, 2022).
Alzheimer’s dementia (1 paper, 2024). "There is only one case describing Alzheimer’s dementia associated with anti-neurochondrin antibody found in the CSF." (PMID 39376559, 2024).
autoimmune encephalitis (1 paper, 2024). Inflammation of the brain secondary to an immune response triggered by the body itself. "have reported one case of anti-neurochondrin positive autoimmune encephalitis with concurrent Sjogren’s disease." (PMID 39376559, 2024). "In addition to the traditional antibody panel for autoimmune encephalitis, some novel antibodies, such as anti-neurochondrin, should also be considered." (PMID 39376559, 2024). "Anti-neurochondrin antibody returned positive in the CSF autoimmune encephalitis panel with a titer of 1:512 (Mayo Clinic TEST ID: ENC2)." (PMID 39376559, 2024).
Chorea (1 paper, 2024). Chorea (Greek for 'dance') refers to widespread arrhythmic involuntary movements of a forcible, jerky and restless fashion. "Additionally, one case of chorea in a child was reported to be associated with anti-neurochondrin antibody in the serum." (PMID 39376559, 2024).
developmental delay (1 paper, 2021). "We report on NCDN missense variants in six affected individuals with variable degrees of developmental delay, intellectual disability (ID), and seizures." (PMID 33711248, 2021).
fragile X syndrome (1 paper, 2012). A genetic syndrome caused by mutations in the FMR1 gene which is responsible for the expression of the fragile X mental retardation 1 protein. "Neurochondrin could also interact with a subset of group I mGluRs, which has been implicated in fragile X syndrome." (PMID 22655085, 2012).
glioblastoma (1 paper, 2024). The most malignant astrocytic tumor (WHO grade IV). "Our results show a promoting effect of NCDN has on the migratory function of glioblastoma cells." (PMID 38230206, 2024). "Then the cell function of NCDN in glioblastoma cell was explored through in vitro cell experiments." (PMID 38230206, 2024). "The expression of NCDN in U87 and U251 cells was significantly upregulated compared to NHA cells, supporting NCDN may have a promoting effect on glioblastoma." (PMID 38230206, 2024).
metastatic colorectal cancer (1 paper, 2026). "Neurochondrin (NCDN) has been recently identified as overexpressed in liver metastatic colorectal cancer (CRC) cells compared to poorly metastatic isogenic counterparts." (PMID 41997895, 2026).
Neurodevelopmental delay (1 paper, 2021). "In conclusion, we identified four different missense variants in NCDN that are functionally relevant in six individuals presenting with a variable degree of neurodevelopmental delay, ID, and seizures." (PMID 33711248, 2021).
ovarian carcinoma (1 paper, 2021). A malignant neoplasm originating from the surface ovarian epithelium. "No malignancies have been reported with anti-neurochondrin and with anti-SEZ6L2 only 1 patient was identified with a ovarian cancer, diagnosed 4 years later." (PMID 34489848, 2021).
tumor (2 papers, 2022 to 2026). "Furthermore, in vivo assays using nude mice and the KM12 cell model demonstrated that NCDN is essential for tumor initiation, growth, and liver metastasis of CRC cells." (PMID 41997895, 2026). "Using our fusion gene database, we identified gene–gene fusions in cfDNA and tumour DNA, such as KDR‐PDGFRA (8%), and NCDN‐PDGFRA (40%) that correspond to the previously reported alterations of PDGFRA in GBM (43% of all our samples)." (PMID 34875133, 2022). "Using our gene–gene fusion database, ChiTaRS 5.0, we identified gene–gene fusions in cfDNA and tumour DNA, such as KDR–PDGFRA and NCDN–PDGFRA, which correspond to previously reported alterations of PDGFRA in GBM (44% of all samples)." (PMID 34875133, 2022).
cancer (1 paper, 2026). A tumor composed of atypical neoplastic, often pleomorphic cells that invade other tissues. "While its cellular function and role in cancer and CRC remain unknown, patient survival data indicate that elevated NCDN levels are associated with poor prognosis." (PMID 41997895, 2026).
neurological disorders (1 paper, 2024). "Further studies are warranted to help expand the clinical spectrum and reveal the pathophysiology of the neurochondrin-associated neurological disorders." (PMID 39376559, 2024). "The distinctive phenotype in our case has not been reported in neurochondrin antibody–related neurological disorders and will contribute to the pool of literature to understand this rare entity." (PMID 39376559, 2024).
NCDN also shares sentences with these, for which no sentence is quoted: cognitive disorder (1 paper); colorectal cancer (1); glioma (1); Intellectual disability (1); spinal muscular atrophy (1).